ABCA1 (ATP binding cassette subfamily A member 1)
Diseases named in the same sentence as ABCA1 in open-access papers (continued):
Sharing a sentence is not in itself a finding about the gene and the disease.
breast carcinoma (36 papers, 2009 to 2026). "ABCA1 expression is high in metastatic breast cancer cell lines and associated with increased metastatic capacity in mouse xenografts and breast cancer patients." (PMID 35327383, 2022). "High expression of ABCA1 correlates with an increased risk of recurrence in colorectal and breast cancer." (PMID 35327383, 2022). "Higher expression of ABCA-1 was associated with higher histological grade in ovarian and breast carcinomas." (PMID 36267880, 2022). "The ATP-Binding Cassette transporter A1 (ABCA1) reverse cholesterol transport channel has been associated with a number of phenotypes in breast cancer, including reduced proliferation and increased metastatic capacity." (PMID 35327383, 2022). "In addition, we inferred that the expression of ABCA1 is associated with the development of breast cancer." (PMID 40297807, 2025). "However, despite the fact that the gene and protein expression of ABCA1 have been linked to a number of cancer phenotypes, little is known about how it is regulated in breast cancer cells." (PMID 35327383, 2022). "Also, a large-scale analysis for screening 3,144 SNPs from 156 breast cancer patients has revealed that ABCA1 and IL12RB2 polymorphism are highly susceptible to radiation-induced dermatitis." (PMID 24594932, 2014). "The in vivo current study revealed a significant overexpression in EGFR gene expression in addition to an obvious reduction in ABCA1 gene expression upon DMBA induced breast cancer in rats." (PMID 39886047, 2025). "In spite of its defensive role in cell protection, ABCA1 mRNA overexpression in breast cancer specimens signifies a poor chemotherapeutic response, leading to low survival rates." (PMID 39886047, 2025). "In breast cancer and prostate cancer, decreased ABCA1 expression facilitates cancer cell proliferation." (PMID 38385857, 2024). "It has been demonstrated that ABCA1 can promote cell metastasis by regulating cholesterol levels, and patients with high ABCA1 expression had shorter times to metastasis in breast cancer." (PMID 37089950, 2023). "In breast cancer, cells can be plastic and convert between epithelial and mesenchymal states, where they exhibit differing levels of ABCA1 expression." (PMID 35327383, 2022). "More work is needed to dissect the multifaceted role of ABCA1 in breast cancer, as well as to understand its contribution to the lipid metabolic reprogramming that seen across a range of cancer states." (PMID 35327383, 2022). "This reveals the mechanism by which ABCA1 is regulated in mesenchymal breast cancer cells and presents a potential avenue by which breast cancer cells acquire metastatic capacity." (PMID 35327383, 2022). "The cholesterol efflux channel ATP-Binding Cassette transporter A1 (ABCA1) has a controversial and poorly understood role in breast cancer." (PMID 35327383, 2022). "Validation of NGS data by qRT-PCR on monocytes isolated out of patients in the independent breast cancer cohort confirmed a significantly increased expression of the ABCA1 gene." (PMID 35237501, 2021). "Conversely, DMHCA increased expression of several LXR target genes, including SCD2, SREBF1, CPD and ABCA1, which positively correlate with increased survival in breast cancer subjects." (PMID 33780491, 2021). "Therefore, the role of ABCA1 in breast cancer is widely understood, including prediction, drug resistance, treatment and prognosis, which provides a promising direction for further research and potential BRCA therapeutic intervention." (PMID 40297807, 2025).
breast carcinoma (continued). "Therefore, we investigated ABCA1 expression in breast cancer cell lines and found that it has higher expression in mesenchymal cells." (PMID 35327383, 2022). "Because the prior experiments suggested that the E-box was repressed in the epithelial state, we predicted from the expression patterns that MYC may repress ABCA1 in epithelial breast cancer cells." (PMID 35327383, 2022). "ABCA1 expression was shown to be regulated by miR‐96 in breast cancer cell lines and AGTR1 was suggested to be a marker of resistance to neoadjuvant chemotherapy in HER2− breast cancer, whereas it was shown to be a therapeutic target in ER+ and ERBB2− breast cases." (PMID 29675884, 2018). "Moreover, expression of SREBP-1c and ABCA1 genes validated the assignation of the lipid phenotype of breast cancer cells." (PMID 23082122, 2012). "As the breast cancer patients were on combined doxorubicin (or epirubicin) and cyclophosphamide therapy for 12 weeks followed by a further 12 weeks on paclitaxel (or docetaxel), we also investigated the effect of physiological levels of cyclophosphamide and paclitaxel on ABCA1." (PMID 26807857, 2016). "Specifically, ABCA1 (a major transporter of lipids out of cells), ABCB1, and BCRP are key players in breast cancer chemoresistance, and ABCB1 and ABCC1 are important indicators of breast cancer prognosis." (PMID 40869256, 2025). "Similar to ABCA1, ABCG1 also plays a crucial role in tumorigenesis in lung cancer and breast cancer." (PMID 39349433, 2024). "In breast cancer, the MEK/ERK/c-Jun/ABCA1 pathway was activated, leading to cholesterol efflux and membrane fluidity enhancement, thereby promoting the epithelial-mesenchymal transition of cancer cells." (PMID 38481816, 2024). "miR-128-2, a pro-apoptotic miRNA was shown to inhibit ABCA1, ABCG1 and RXRα mRNA and protein expression in cell lines such as MCF-7 breast cancer and HepG2 liver hepatocellular carcinoma." (PMID 32577155, 2020). "ATP-binding cassette transporter ABCA1, a gene involved in the cellular lipid removal pathway is over-expressed in resistant M14 melanoma as compared to the sensitive MDA-MB-231 breast cancer cells." (PMID 20030852, 2009). "Although ABCA1 expression is also downregulated by c-Myc in breast cancer, no remarkable difference in c-Myc expression was observed between EpH4 and EpH4-Snail cells, indicating that c-Myc is not likely involved in ABCA1 expression in EpH4-Snail cells." (PMID 41521893, 2026). "For instance, ABCA1 is found to be one of the genes shared between high LDL and breast cancer." (PMID 38947022, 2024). "Breast cancer induction declared a significant reduction in the expression of ABCA1 gene (0.18-fold change) as compared with negative control group (onefold change)." (PMID 38827789, 2024). "This study investigated ABCA1 and ABCG1 in connection to breast cancer chemoresistance." (PMID 38827789, 2024). "Of all the ligand-responsive genes, 83 (23 upregulated and 60 downregulated) were responsive in all four breast cancer cell lines, including known LXR target genes such as ABCA1 and ABCG1, and they represent candidate mechanisms for the anti-proliferative effects of LXR ligands in these cell lines." (PMID 23809258, 2013). "Furthermore, we deciphered its transcriptional regulatory program and report that ABCA1 expression is low in epithelial, non-metastatic breast cancer cells via MYC-mediated repression of an E-box element in its proximal promoter." (PMID 35327383, 2022).
breast carcinoma (continued). "To determine whether the increase in ABCG1 and ABCA1 expression induced by 4-cholesten-3-one was LXR-dependent, we decided to suppress LXR activity in breast cancer cells using an SR9238 inverse agonist and to subsequently study the mRNA expression of LXR target genes, ABC transporters." (PMID 31477154, 2019). "But, ABCA1 is upregulated in high LDL and downregulated in breast cancer, suggesting that inhibitions of this gene might not lead to desired treatment outcome for breast cancer." (PMID 38947022, 2024). "Moreover we have previously analyzed the breast cancer cell lines MCF-7 and MDA-MB-468 and found that both, similar to MDA-MB-231 cells, are Curcumin sensitive and do not express ABCA1 (our unpublished data)." (PMID 20030852, 2009).
Hypercholesterolemia (34 papers, 2008 to 2025). An increased concentration of cholesterol in the blood. "DNA methylation in the ABCA1 promoter region is associated with prior history of CAD in patients with familial hypercholesterolemia." (PMID 34837967, 2021). "In contrast, an Egyptian study reported that the ABCA1 TT genotype was associated with hypercholesterolemia and diminished HDL in T2DM patients, which could be due to the associated increased BMI found in this genotype." (PMID 36553543, 2022). "The clearest evidence for a role of excessive myelopoiesis in neutrophilia and monocytosis comes from studies of animal models with hypercholesterolemia and genetic deficiency in genes involved in cholesterol efflux from hematopoietic cells such as Abca1−/−/Abcg1−/− or Apoe−/− mice." (PMID 32086626, 2020). "Also, in another study in the patients with familial hypercholesterolemia it was indicated that ABCA1 gene promoter methylation was associated with CAD occurrence." (PMID 30046619, 2018). "In summary, the experimental results indicate that the BYHWT alcohol precipitation, 50% alcohol, and 75% alcohol components can modulate the PPARγ/LXRα/ABCA1 pathway in hypercholesterolemia mouse model to promote CHO metabolism." (PMID 40678621, 2025). "In the hypercholesterolemia environment, miR-302a is up-regulated to inhibit the expression of ATP-binding cassette transporter A1 (ABCA1), to stimulate the lipid-cleaning function of macrophages with cholesterol accumulation in plaques." (PMID 35634335, 2022). "In a study of patients with familial hypercholesterolemia, ABCA1 promoter methylation was confirmed to be related to the occurrence of hypercholesterolemia." (PMID 35308237, 2022). "The DNA methylation level of ABCA1 affects high density lipoprotein cholesterol (HDLC) levels in patients with familial hypercholesterolemia." (PMID 32300590, 2020). "Nonetheless, the association between ABCA1 DNA methylation and CAD that we first observed in FH subjects has now been replicated in men with common hypercholesterolemia." (PMID 25093045, 2014). "PON1 not only affects the process of cholesterol efflux via an ABCA1 dependent pathway, but also shows an antioxidative role in familial hypercholesterolemia; so its activity is an adjunctive index of altered lipoprotein metabolism." (PMID 24971380, 2014). "This study proved that the alcohol precipitation group and 75% group components can enhance RCT by upregulating the PPARγ/LXRα/ABCA1 signalling pathway, thus reducing the lipid level in hypercholesterolemia mouse model and improving lipid accumulation in hepatocytes." (PMID 40678621, 2025). "Therefore, this study was mainly conducted to confirm that different components of BYHWT reduced blood lipid levels in hypercholesterolemia mouse model through the PPARγ/LXRα/ABCA1 pathway." (PMID 40678621, 2025). "Therefore, as stimulators of macrophage inflammasomes, NETs are closely related to hypercholesterolemia induced by decreased ABCA1 expression and cholesterol effusion." (PMID 33557767, 2021). "Three statistical models were used to test the genotypic associations of ABCA1 rs2230806 polymorphisms with DKD with or without hypercholesterolemia." (PMID 33426085, 2020). "Our results suggest that LXR-α rs7120118 is significantly associated with a higher risk of DKD, and ABCA1 rs2230806 is significantly associated with a higher risk of DKD without hypercholesterolemia in Chinese Han individuals." (PMID 33426085, 2020). "Indeed, we have recently shown that a higher DNA methylation level at the ABCA1 gene promoter locus was associated with lower HDL-C levels and a previous history of CAD in familial hypercholesterolemia (FH)." (PMID 25093045, 2014). "Moreover, unlike the situation reported with ABCG1-myeloid deficiency where the tumor protective effect was observed under conditions of hypercholesterolemia, this does not appear to be a prerequisite to elicit tumor protection with ABCA1-myeloid deficiency." (PMID 29069761, 2017).
Hypercholesterolemia (continued). "Therefore, the focus of this study was to investigate the mechanism of liver CHO accumulation induced by HFD in hypercholesterolemia mouse model and the effects of different components of BYHWT on the PPARγ/LXRα/ABCA1 pathway in these mice." (PMID 40678621, 2025). "ABCA1 rs2230806 is significantly associated with the risk of DKD and confirms its minor allele G as a higher risk factor for DKD without hypercholesterolemia." (PMID 33426085, 2020). "DNA methylation at the ABCA1 promoter has been shown to negatively correlate with HDL levels and incidence of coronary artery disease (CAD) in individuals with familial hypercholesterolemia, and ABCA1 promoter methylation levels have been shown to increase with age." (PMID 28032115, 2016).
prostate carcinoma (29 papers, 2008 to 2025). A carcinoma that arises from epithelial cells of the prostate gland. "Increased transcription of ABCA1 was associated with CAV‐1 stabilization in prostate cancer‐derived cells." (PMID 30098223, 2018). "Another group validated this regulation and showed that miR-27a promotes prostate cancer cell proliferation by targeting ATP-binding cassette transporter 1 (ABCA1) and PDS5 cohesin associated factor B (PDS5B), suggesting the oncogenic role of miR-27a." (PMID 28783103, 2017). "Indeed, ABCA1 downregulation has been observed in prostate cancers, and suppression of ABCA1 expression by oncogenic mutations or loss-of-function mutation has been linked to an accumulation of mitochondrial cholesterol and malignant cell transformation." (PMID 35237673, 2022). "Numerous studies have demonstrated that ABCA1 was associated with the development of a variety of cancers, including colon cancer, myeloproliferative neoplasms, ovarian cancer, prostate cancer, and melanoma." (PMID 36713557, 2022). "Hypermethylation of ABCA1 is associated with high-grade prostate cancer." (PMID 25628764, 2015). "PPARδ promotes the formation of xenograft tumors derived from prostate cancer cells by modulating ATP-binding cassette transporter 1 (ABCA1) gene." (PMID 38933330, 2024). "In prostate cancer cells, the reduced expression of ABCA1 with promoter hypermethylation maintains elevated intracellular cholesterol levels, contributing to aggressive prostate cancer progression." (PMID 38060103, 2023). "Loss of CYP27A1 has been determined to dysregulate cholesterol homeostasis in prostate cancer; the same was found for the gene ABCA1." (PMID 35453307, 2022). "PPARδ induces xenograft tumor growth of prostate cancer cells by regulating the ATP binding cassette transporter 1 (ABCA1) gene." (PMID 34775964, 2021). "ABCA1 promoter hypermethylation and downregulation of ABCA1 expression has been found to contribute to aberrant accumulation of cholesterol in prostate cancer cell lines." (PMID 33066132, 2020). "One study pointed out that ABCA1 down regulation was evident in prostate cancer due to promoter hypermethylation, leading to high intracellular cholesterol levels and an environment conductive to tumor progression." (PMID 31598156, 2019). "It has been demonstrated that lycopene inhibits prostate cancer cell proliferation via the PPARγ-LXRα-ABCA1 pathway." (PMID 29324670, 2018). "The ABCA1 gene promotor is hypermethylated in the tissues of prostate cancer, suppressing its expression." (PMID 30283400, 2018). "MiR-27a has also been identified to represses ATP-Binding Cassette Sub-Family A Member 1 (ABCA1) function in prostate cancer and in Huh-7.5 cells." (PMID 27351287, 2016). "Our results were also confirmed by a recent finding that ABCA1 is epigenetically silenced by promoter methylation in prostate cancer cells." (PMID 25628764, 2015). "ABCA1 has been found to promote cell proliferation in human androgen-dependent prostate cancer LNCaP cells." (PMID 25050621, 2014). "ABCA1 may have a dual role in cancer, with ABCA1 showing anti-cancer effects in breast and prostate cancers, but pro-cancer effects in colorectal, bladder and melanoma cancers." (PMID 36713557, 2022). "For example, ABCA1 is an auspicious therapy target in prostate cancer." (PMID 33777800, 2021). "ABCA1 has been reported to be upregulated at the mRNA and protein level in triple negative breast cancer and ovarian cancer, but downregulated in prostate cancer." (PMID 33066132, 2020). "ABCA1 expression levels are inversely correlated with tumor aggressiveness in prostate cancer." (PMID 30283400, 2018). "Interestingly, recent studies show that LXR agonist inhibits tumor growth and progression of LNCaP prostate cancer cells and androgenic inhibition of ABCA1 is involved in the regulation of prostate cancer growth." (PMID 19787078, 2008).
prostate carcinoma (continued). "Patients with positive family history for prostate cancer showed high levels of EGFR, TG, TC, LDL, alkaline phosphatase (ALP), but low AKR1C4, SLDLRP1, CAV1 and ABCA-1 levels." (PMID 36480560, 2022). "Several lines of evidence have demonstrated that activation of p38 is able to up-regulate the expression of ABCA1 and ABCG1 in macrophages and prostate cancer epithelial cells." (PMID 35902881, 2022). "Interestingly, aberrant ABCA1 promoter methylation was more prevalent in intermediate- and high-grade cancers than in low-grade cancers, suggesting that downregulation of ABCA1 could play a role in the development and progression of prostate cancer." (PMID 33066132, 2020). "Impaired LXR-mediated regulation of ABCA1 and ABCG1 involved in cholesterol efflux has been proposed as a defect in LnCaP and PC3 prostate cancer cell lines that contributes to cholesterol elevation." (PMID 23919967, 2013). "Analyses of prostate cancer and benign prostate tissues have shown that ABCA1 promoter hypermethylation occurs frequently in prostate cancer but not in benign prostatic tissue." (PMID 33066132, 2020). "Concerning malignant cells rather than normal cells, the significance of ABCA1 in the control of cellular proliferation is revealed by using a human prostate cancer cell line LNCaP." (PMID 26452260, 2015). "Compared to the normal cells, prostate cancer cells showed high expression of cholesterol-producing HMGCR but failed to express the major cholesterol exporter ABCA1." (PMID 22761797, 2012).